GSK3B (glycogen synthase kinase 3 beta)
Diseases named in the same sentence as GSK3B in open-access papers (continued):
Sharing a sentence is not in itself a finding about the gene and the disease.
cardiac hypertrophy (continued). "Our findings reveal that miR-26a-5p promotes PE-induced cardiac hypertrophy by regulating GSK3β and activates autophagy in vitro and in vivo, which may provide a novel insight into the pathogenesis of cardiac hypertrophy." (PMID 33240671, 2020). "In addition, cardiac-specific mindin overexpression attenuates cardiac hypertrophy by blocking AKT/GSK3β and TGF-β1-Smad signaling." (PMID 31998553, 2020). "Previous studies from our laboratory or others have indicated that activated AKT directly phosphorylates and inactivates GSK3β, a series of processes that regulate the general protein translational machinery and participate in the development of pressure overload‐induced cardiac hypertrophy." (PMID 30741414, 2019). "Pioglitazone was previously shown to regulate GSK-3β levels against cardiac hypertrophy in vivo." (PMID 30965670, 2019). "Both cardiac dysfunction and hypertrophy are reversed by SB‐216763, a GSK‐3β inhibitor." (PMID 29600538, 2018). "To test whether GSK3β acetylation plays a role in the development of heart failure, we first created a mice model of cardiac hypertrophy." (PMID 29504933, 2018). "Activation of GSK3β antagonizes the development of cardiac hypertrophy." (PMID 29504933, 2018). "To test whether GSK3β activity is reduced in our cardiac hypertrophy model, we immunoprecipitated GSK3β from the heart lysates and assessed in vitro activity of GSK3β against the peptide of glycogen synthase (GS)." (PMID 29504933, 2018). "However, accumulating evidence indicates that protein kinase B (AKT)/glycogen synthase kinase-3β (GSK3β) and mitogen-activated protein kinases (MAPKs) play key roles in the development of cardiac hypertrophy." (PMID 28127304, 2017). "However, we have evidence that GRK2 regulates NFAT and induction of cardiac hypertrophy via Akt and GSK3β." (PMID 28759639, 2017). "In conclusion, PIO could inhibit cardiac hypertrophy via attenuation of AKT/GSK3β and MAPK pathways." (PMID 27110236, 2016). "GSK-3β is detected in two states in the cytoplasm: in a free form or in a complex with APC/Axin to regulate the activity of the canonical Wnt/β-catenin pathway, which is associated with cell cycle control, survival, and cardiac hypertrophy." (PMID 27977752, 2016). "GSK-3β was the first negative regulator of cardiac hypertrophy to be identified." (PMID 24971153, 2014). "Notably, GSK‐3β functions as a negative regulator of cardiac hypertrophy." (PMID 40753540, 2025). "Mechanical stimulation could activate Akt/GSK3β, and then promote myocardial hypertrophy." (PMID 36834623, 2023). "In addition, SGK3 could also participate in the development of cardiac hypertrophy and fibrosis by regulating the phosphorylation of GSK3β." (PMID 36531961, 2022). "However, it is possible that cardiac piRNA expression has downstream effects on cellular signaling pathways that involve GSK3β, which is a known repressor of cardiac hypertrophy by phosphorylating proteins involved in cell proliferation such as β-catenin and NFATC4." (PMID 33673453, 2021). "Above results indicated that miR-26a-5p could promote cardiac hypertrophy by regulating GSK3β." (PMID 33240671, 2020). "However, the role played by calcineurin-NFAT and GSK-3β signaling in testosterone-induced cardiac hypertrophy has remained unknown." (PMID 27977752, 2016). "Overexpression of GSK-3β may prevent the development of cardiac hypertrophy." (PMID 25780423, 2015). "Also, treatment with either AT1 receptor blocker or tempol attenated STZ-induced cardiac hypertrophy and fibrosis by attenuating the inactivation of GSK3β and thus preventing the nuclear translocation of NFATc3, and also attenuated PKCβ2 and p38 MAPK signaling 28 days after STZ injection." (PMID 22043204, 2010). "Several signaling pathways involved in cardiac hypertrophy include the MAPK signaling, PI3K/AKT signaling, Gsk3β signaling, NF-κB signaling, calcineurin/NFAT signaling and CaMK II signaling pathways." (PMID 40610735, 2025).
cardiac hypertrophy (continued). "Mechanistic studies indicated that MARCH5 directly interacted with Akt, enhancing the phosphorylation of Akt, mTOR and Gsk3β, thereby increasing GATA4 expression and aggravating cardiac hypertrophy." (PMID 40753540, 2025). "It was observed that PI3K, AKT, GSK3β, mTOR, P70S6K, and eIF-4E were significantly phosphorylated in TAC mice, suggesting that PI3K-Akt signaling pathway was indeed activated in cardiac hypertrophy." (PMID 33778070, 2021). "SIRT2 was reported to repress cardiac hypertrophy via diverse mechanisms, including activation of AMPK and repression of GSK3b and NFATc2." (PMID 33611744, 2021). "As expected, it was observed that PI3K, AKT, GSK3β, mTOR, P70S6K, and eIF-4E were significantly phosphorylated in the TAC group, suggesting that PI3K-Akt signaling pathway was indeed activated in cardiac hypertrophy." (PMID 33778070, 2021). "Thus, our findings revealed that miR-26a-5p could promote cardiac hypertrophy by regulating GSK3β." (PMID 33240671, 2020). "MiR-21-3p protects against cardiac hypertrophy in male mice by regulating histone deacetylase 8 (HDAC8) expression and Akt/Gsk3β signaling, important for growth control in the cardiovascular system." (PMID 32252821, 2020). "GA significantly ameliorated cardiac function and inhibited cardiac hypertrophy and fibrosis by disruption of PI3K–Akt–GSK3β and MEK1/2–ERK1/2– GATA4 signaling and via Ang II stimulation." (PMID 33328989, 2020). "Our results showed that inhibiting SLC26A4 suppressed cardiac hypertrophy, as determined by the down-regulation of ANP and BNP and the up-regulation of GSK-3β." (PMID 31998553, 2020). "The results demonstrated that galangin significantly ameliorated cardiac function and inhibited cardiac hypertrophy and fibrosis by disruption of PI3K–Akt–GSK3β and MEK1/2–ERK1/2–GATA4 signaling after pressure overload in vivo and Ang II‐stimulation in vitro." (PMID 30741414, 2019). "A previous study showed that the acetylation of GSK3β increases in pathological cardiac hypertrophy and that SIRT2 binds to, deacetylates and activates GSK3β." (PMID 31105527, 2019). "Thus, lithium may increase physiological cardiac hypertrophy by inhibiting GSK-3β activity." (PMID 28115595, 2017). "In line with this, Wortmannin treatment prevented GRK2 induced Akt and GSK3β phosphorylation, suggesting an essential role for GRK2-PI3Kγ interaction in GRK2 mediated cardiac hypertrophy." (PMID 28759639, 2017). "Our data show that enhanced GRK2 expression triggers cardiac hypertrophy by GRK2-PI3Kγ mediated Akt phosphorylation and subsequent inactivation of GSK3β, resulting in enhanced NFAT activity." (PMID 28759639, 2017). "Numerous studies have implicated that activation of protein kinase B (AKT)/glycogen synthase kinase-3β (GSK3β) and mitogen-activated protein kinase (MAPK) was closely involved in the process of cardiac hypertrophy." (PMID 27110236, 2016). "Other studies reported that allicin protected cardiac function and prevented the development of cardiac hypertrophy through ROS-dependent mechanism involving multiple intracellular signaling (ERK1/2, JNK1/2 and PI3/Akt/GSK3β signaling pathways)." (PMID 27990229, 2016). "We and others previously revealed that several signaling pathways are involved in the regulation of cardiac hypertrophy, including the MAPK, calcineurin/nuclear factor of activated T cells (NFAT), and Akt/GSK-3β signaling cascades." (PMID 24763737, 2014). "The downstream targets of AKT include GSK3β, mTOR,FOXO transcription factors and NFκB, all of which are involved in cardiac hypertrophy." (PMID 23349709, 2013). "Consistent with molecular signalling events known to occur under conditions of physiological cardiac hypertrophy, there were three PI3K/AKT signalling pathway molecules (Gsk3b, Nfkbia, and Ppp2r1a) altered in exercised mice and rats." (PMID 20003209, 2009). "HDAC2 may be involved in the pathogenesis of cardiac hypertrophy via modulation of the PI3K, Akt and GSK3β signalling pathway." (PMID 40497340, 2025).
cardiac hypertrophy (continued). "Herein, we found that USP38 positively regulates pathological cardiac hypertrophy and remodeling by preventing the proteasomal degradation of p-TBK1, leading to the activation of Akt-GSK3β/mTOR signaling pathway and the acceleration of heart failure progression." (PMID 38481817, 2024). "The stable activation of GSK-3β by augmented O-GlcNAcylation is likely to induce heart failure via the lack of cardiac hypertrophy in Ogt-Tg mice after TAC4W." (PMID 37033243, 2023). "However, when GSK3β’s kinase activity is inhibited it cannot phosphorylate NFATC4, which remains in the nucleus—promoting cardiac hypertrophy." (PMID 33673453, 2021). "A large number of studies suggest that PI3K/Akt/GSK3β signaling is cardio-protective and mediates physiological rather than pathological cardiac hypertrophy." (PMID 32252821, 2020). "Our findings revealed that SLC26A4 increases cardiac hypertrophy, and inhibiting SLC26A4 could decrease the release of ANP/BNP and promote the expression of GSK-3β in vitro and in vivo." (PMID 31998553, 2020). "Recent studies demonstrate a functional role of GSK3β in negative modulation of cardiac hypertrophy and in the setting of cardiac ischemic disease 48-50." (PMID 32210724, 2020). "Our study found that SLC26A4 is involved in cardiac hypertrophy and inhibiting SLC26A4 could decrease the release of ANP or BNP and promote the expression of GSK-3β in vivo and in vitro." (PMID 31998553, 2020). "Our results demonstrated that FKBP12.6 protects heart from AngII‐induced cardiac hypertrophy through preventing the activations of the Ca2+/calmodulin‐dependent signalling pathways such as calcineurin/NFATc4, CaMKII/MEF‐2, AKT/GSK3β/NFATc4 and AKT/mTOR pathways." (PMID 29682889, 2018). "Thus, GSK-3β inhibition promotes the nuclear residence of NFAT and thereby induces cardiac myocyte hypertrophy." (PMID 27977752, 2016). "GSK-3β mediates antihypertrophic effects through multiple mechanisms; therefore, GSK-3β deactivation during cardiac hypertrophy might represent a potential mechanism for modulating the hypertrophic activity of cardiomyocytes." (PMID 24971153, 2014). "We further demonstrated that the absence of Nek6 promoted cardiac hypertrophy, fibrosis, dilatation and cardiac dysfunction, which was accompanied by the significant activation of Akt/GSK-3β signaling in an experimental model of TAC." (PMID 24763737, 2014). "Wnt activation brought by GSK3β inhibition may promote cancer phenotypes, cardiac hypertrophy as well as other non-specific deleterious events." (PMID 39392548, 2025). "In cardiac hypertrophy, the PI3K-Akt signaling pathway is activated by many types of cellular stimuli or toxic insults to regulate fundamental cellular processes including protein synthesis, proliferation, and survival, via its downstream signals, such as AKT, GSK3β, mTOR, P70S6K, and eIF-4E." (PMID 36704572, 2023). "Collectively, the GSK-3β signaling pathway, but not NF-κB, may be involved in cardiac hypertrophy after TAC4W that induces cardiac dysfunction." (PMID 37033243, 2023). "Furthermore, signal transduction validation in vivo and in vitro demonstrated that Trim44 deficiency in the myocardium inhibited the activation of cascade pathways involved in cardiac hypertrophy, AKT/mTOR/GSK3β/P70S6K, especially response to pathological stress." (PMID 35855640, 2023). "In conclusion, for the first time, we showed that DBZ robustly protects against cardiac hypertrophy in rats after TAC surgery and in cardiomyocytes treated with Ang II, which is mostly due to the antioxidant and anti-ER stress properties of DBZ, via the mTOR/GSK3β(Ser9)/β-TrcP/NRF2 pathway." (PMID 35185583, 2022). "In vivo and in vitro experiments confirmed that piperine activates GSK-3β by blocking AKT activation, which consequently inhibits the conversion of neonatal rat cardiac fibroblasts to myofibroblasts, reduces α-SMA and collagen accumulation, and eventually alleviates cardiac hypertrophy and fibrosis." (PMID 33052244, 2020).
cardiac hypertrophy (continued). "Although the adaptive/maladaptive roles of GSK3β are not entirely understood and may depend on the type of cardiac damage, a large body of evidence suggests that GSK3β acts as a negative regulator of cardiac hypertrophy." (PMID 24310814, 2014). "Given that the lack of cardiac hypertrophy was observed in the heart tissues of Ogt-Tg mice, it is conceivable that the inhibition of NFAT via GSK-3β by O-GlcNAcylation aggravated the pressure overload-induced heart failure after TAC4W." (PMID 37033243, 2023). "Although DBZ reportedly ameliorates lipopolysaccharide (LPS)-induced neuroinflammation and ischemic stroke via Akt/GSK3β/NRF2 pathway in rats, its functions in cardiac hypertrophy have not yet been studied." (PMID 35185583, 2022).
neuroblastoma (104 papers, 2006 to 2025). Neuroblastoma (NB) is the most common solid, extracranial childhood tumor. "Some authors have described an increase of tau phosphorylation through Akt/Glycogen synthase kinase-3 beta (GSK-3β) pathway in neuroblastoma cells when DJ-1 was mutated." (PMID 35182267, 2023). "Tideglusib was found to be effective in preventing cell death caused by ethacrynic acid in neuroblastoma cells by inhibiting GSK-3β activity, which resulted in a considerable reduction in TDP-43 phosphorylation." (PMID 34445680, 2021). "GSK3β is also an interesting potential target for neuroblastoma therapy, as it has been implicated in cell growth inhibition and apoptosis in various cancers." (PMID 32158616, 2020). "Our data demonstrate that DOX-induced apoptosis was enhanced by deficiency of SIRT1 and AROS and increased by GSK3β expression in human neuroblastoma SH-SY5Y cells." (PMID 32158616, 2020). "A study in human neuroblastoma SK-N-BE cell line and TgCRND8 mouse showed that GSK3β gene's promoters can be hypomethylated by inhibiting methylation activity through B vitamin deficiency and such hypomethylation results in the overexpression of GSK3β." (PMID 24367332, 2013). "Indeed, a recent publication from Adinolfi’s group nicely demonstrated that P2X7R triggers PI3K/Akt activation in neuroblastoma cell lines and derived tumors, thus affecting the main downstream effectors implicated in neuroblastoma progression: GSK3β/MYCN and HIFα/VEGF pathways." (PMID 26687764, 2015). "SITR1 cooperates with the activity regulator AROS to inhibit the acetylation of GSK3β, inactivating GSK3β, which weakens doxorubicin‐mediated apoptosis in neuroblastoma treatment, leading to tumour resistance." (PMID 39778006, 2025). "Using human neuroblastoma cells, we further identified the involvement of Glycogen Synthase Kinase-3 beta (GSK3β), a serine-threonine kinase downstream of c-Abl, likely being responsible for the direct phosphorylation of Ser129." (PMID 40988055, 2025). "In neuroblastoma cells the CNTF-induced PI3K-Akt-GSK3β pathway is important for survival and neurite growth." (PMID 39592934, 2024). "A previous study using human and mouse neuroblastoma cell culture suggests that inhibition of GSK-3β by AR-A014418 decreases APP cleavage by BACE1, reducing the production of Aβ peptides." (PMID 38574297, 2024). "On the other hand, in human SH-SY5Y neuroblastoma cells, lithium inhibits GSK3β, contributing to antiapoptotic signaling mechanisms." (PMID 36836894, 2023). "doi: 10.1002/2211-5463.12620 2 Chen J, Wang P, Cai R, Peng H, Zhang C and Zhang M SLC34A2 promotes neuroblastoma cell stemness via enhancement of miR-25/Gsk3β-mediated activation of Wnt/β-catenin signaling." (PMID 37219054, 2023). "Orphan drug status was granted for the BfIM 70 by the FDA for the treatment of neuroblastoma, as it is a potent growth suppressor of neuroblastoma cells through GSK-3β inhibition." (PMID 37764999, 2023). "In this regard, previous studies had indicated that APPsα overexpression in neuroblastoma cells can inhibit GSK3β and that incubation of primary neurons with recombinant APPsα (recAPPsα) resulted in downregulation of CDK5 expression and activity in vitro." (PMID 36779015, 2023).